HDAC2 (histone deacetylase 2)
Diseases named in the same sentence as HDAC2 in open-access papers (continued):
Sharing a sentence is not in itself a finding about the gene and the disease.
cancer (continued). "While all four classes of HDACs have been implicated in various cancers, Class I HDACs (HDAC1, HDAC2, HDAC3, and HDAC8) are generally considered the most directly and frequently associated with tumorigenesis and are often the primary targets in initial cancer therapeutic strategies." (PMID 41440016, 2025). "This may be some sort of rebound mechanism to overcome the strong inhibition of HDACs, because literature evidence indicates that SAHA was able to reduce the levels of HDAC2 and 4 in cancer cells." (PMID 40941018, 2025). "Given the importance of HDACs and E3 ligases in cancer biology, the proposed feedback loop involving HDAC2 and PJA2 may represent a common regulatory mechanism in other cancers." (PMID 39928532, 2025). "Moreover, DNMT3a and HDAC2 enzymes were shown to be involved in the cancer stem phenotype in OS, and HDAC2 expression was suggested as a therapeutic target." (PMID 40868849, 2025). "These drugs have brought new hope to cancer treatment, and HDAC2, as an important target, may provide potential options for future cancer therapies." (PMID 40083325, 2025). "In support of these observations, we found that the most robust and stringent positive associations with cancer stemness were evidenced for HDAC2 expression, whereas a negative association was demonstrated for HDAC7 expression." (PMID 39063083, 2024). "Importantly, we found that serous tumors (borderline and carcinomas) displayed increased HDAC-2 immunoreactivity; however, this correlation was of marginal significance, probably because of the low number of non-serous tumors included in our investigation." (PMID 38790909, 2024). "This implies that high levels of HDAC2 could predict the poor prognosis of patients with HCC and suggests the role of HDAC2 in cancer initiation and progression." (PMID 36968022, 2023). "Several reports suggested that HDAC2 is a prognostic marker of various cancers." (PMID 36968022, 2023). "More precisely, caffeic acid better interacted with HDAC2 in silico and decreased its activity both ex vivo and in vitro, hence inducing cancer cell death by ROS generation, cell cycle arrest in S and G2/M phases, as well as caspase-3 mediated apoptosis induction." (PMID 37190151, 2023). "This review also presents HDAC2 as a valuable target for developing anti-cancer drugs." (PMID 36968022, 2023). "In addition, we explored the interactions of the PR/TRPS1/HDAC2 complex after MPA treatment in cancer cell lines." (PMID 37344459, 2023). "Thus, HDAC2 inhibitors, as a novel type of anticancer drug, have also displayed their potential as a sensitizer for cancer immunotherapy." (PMID 36765782, 2023). "Our multi-approach comparative analysis could be useful in the exploration of HDAC2 deregulation as a cancer driver." (PMID 37046620, 2023). "Thus, a molecular network involving HDAC2 has been considered to serve as a target for developing anti-cancer drugs." (PMID 37764768, 2023). "The domain of HDAC2 that confers resistance to anti-cancer drugs should be identified." (PMID 36968022, 2023). "Collectively, we successfully identified a novel CARM1/HDAC2 dual-targeting inhibitor and it may play an essential value in the treatment of malignant tumour." (PMID 37528657, 2023). "Collectively, these findings underscore the pivotal role of HDAC2 in cancer biology." (PMID 37495623, 2023). "Thus, it is necessary to develop anti-cancer drugs targeting HDAC2 by completely understanding the mechanisms of HDAC2-promoted cancer cell proliferation and anti-cancer drug resistance and the genes regulated by HDAC2." (PMID 36968022, 2023). "Thus, the inhibition and downregulation of HDAC2 suppressed cancer cell proliferation by regulating the cell cycle, apoptosis, signaling, and metabolic pathways." (PMID 36968022, 2023). "The roles of HDAC2 in tumorigenesis and anti-cancer drug resistance are discussed in this review." (PMID 36968022, 2023).
cancer (continued). "Additionally, new evidence has shown that HDAC2 inhibitors have anti-cancer properties, including in cases of HCC, making them a promising new drug for treating HCC." (PMID 37716965, 2023). "Screening inhibitors based on the full-length HDAC2 structure may lead to the discovery of authentic HDAC2 inhibitors with anti-cancer effects." (PMID 36968022, 2023). "HDAC2 is a drug target as it is known to be upregulated in cancers and neurodegenerative disorders." (PMID 35051665, 2022). "In addition to MCM2 to MCM7, six downstream oncogenic targets of c-MYC implicated in cancer survival and metabolism including PSMA1, PSMA6, PSMB2, HDAC2, LDHA and SPRING were positively correlated with IFITM3 in 71 GC specimens using the Cho dataset." (PMID 35941699, 2022). "Thus, a specific inhibitor of HDAC2 would be a promising pharmacologic tool for Treg repression in cancer therapy." (PMID 35795673, 2022). "Importantly, we further demonstrate that catalytic inactivation of HDAC1 or HDAC2 sensitizes cells to specific cancer drugs." (PMID 35994477, 2022). "In summary, BUB1B was highly expressed in NPC, and HDAC2 may affect cell cycle by regulating BUB1B to promote cancer progression." (PMID 36577966, 2022). "Therefore, we identified the regulation mechanism of the growth inhibition through cancer metabolism changes of GBM by HDAC2 knockdown in this study." (PMID 35260183, 2022). "Human HDAC2 is one of the key nuclear-localised enzymes, its activity is important in development and it has been shown to be a relevant drug target in a number of diseases such as carcinomas and neurodegenerative disorders." (PMID 35051665, 2022). "Moreover, we uncovered that miR-503-5p was lowly expressed in ESCC cancer tissues, and miR-503-5p and HDAC2 was negatively connected." (PMID 33926524, 2021). "For this reason, we focused on four MYC-interacting proteins, i.e., Promyelocytic leukemia protein (PML), Glycogen synthase kinase-3 beta (GSK3B), Cyclin-Dependent Kinase Inhibitor 2A (CDKN2A), and Histone deacetylase 2 (HDAC2), which were reported to be mis-regulated in cancer in previous studies." (PMID 36303724, 2021). "The results manifested that HDAC2 expression was elevated in ESCC cancer tissues and cells." (PMID 33926524, 2021). "Moreover, HDAC2 has been characterized as a critical regulator in tumorigenesis, cell cycle progression and immune escape of cancer cells." (PMID 34365463, 2021). "Moreover, histone hypoacetylation (mainly H3K9/K14) in the promoter of CDKN1C induced by the overexpression of HDAC1 and HDAC2 in cancer cells is another reason for the low expression of CDKN1C in cancers." (PMID 34650035, 2021). "We demonstrated for the first time that histone H2AZ could be acetylated at lysine residues 4 and 7 by HDAC2 in human cancer cells." (PMID 31993801, 2020). "Furthermore, the ectopic expression of HDAC2 in HDAC2 mutant cancer cells inhibited tumor cell growth in vitro and in vivo." (PMID 33267897, 2020). "A previous study demonstrated that HDAC2 inhibitor VPA reduced induction of RIG-I expression in different cancer cell lines by decitabine, suggesting that HDAC2 might be involved in regulation of RIG-I expression." (PMID 32832570, 2020). "lncRNA-EPB41L4A-AS1 via mediating nucleolar translocation of HDAC2 could regulate glycolysis and glutaminolysis in cancer." (PMID 33123468, 2020). "Histone deacetylase (HDAC2) belongs to the hydrolase family and a promising target for cancers." (PMID 31312074, 2019). "Therefore, we believe that the p300/YY1/miR-500a-5p/HDAC2 signalling axis plays important roles in cancer development." (PMID 30737378, 2019). "This revealed a sub-network linking eight transcriptional regulators of which most already have been related to cancer progression, including HDAC2, BPTF, BRF1, TAF11, TCF12, and FOS31,32, but also a prominent role for SMADs that are normally driven by TGF-β33." (PMID 31278301, 2019).
cancer (continued). "Therefore, the inhibition of HDAC2 by VPA reverses the sensitivity of cancer cells to chemo and radiation therapy." (PMID 30909413, 2019). "There is more evidence for HDAC2 overexpression in certain cancers compared with normal tissues." (PMID 31805977, 2019). "Sp1 and Sp3 regulate EGFR activity through interacting with HDAC1 and HDAC2 in cancer cells." (PMID 31196210, 2019). "Furthermore, epigenetic silencing of the retinoblastoma gene operated by histone deacetylase 2 (HDAC-2) drives the transdifferentiation of M-MDSCs into PMN-MDSCs in cancer." (PMID 31535085, 2019). "CAGE can bind to HDAC2 and confers resistance to various anti-cancer drugs." (PMID 30583572, 2018). "HDAC2 has been reported to be aberrantly expressed in diverse cancers." (PMID 28538837, 2017). "We next investigated the effect of Hdac1 and Hdac2 ablation in the Eμ-myc cancer background, and in particular whether they have tumor suppressive or tumor promoting functions during Eμ-myc tumorigenesis." (PMID 27886239, 2016). "CAGE, through interaction with HDAC2, confers resistance to anti-cancer drugs." (PMID 26863629, 2016). "It is highly likely that the overall response to conventional treatment may be less robust in patients that strongly express HDAC2 in their cancer cells." (PMID 27283986, 2016). "Aberrant expression patterns of HDAC2 are found in a number of cancers including CRC." (PMID 27283986, 2016). "Interestingly, the fact that the epi-mark of cancer progression, H4K16ac, is specifically downmodulated in HDAC2-silenced cells suggests decreased tumorigenicity, further corroborated by the lower clonal potential of these cells." (PMID 25473896, 2015). "Whether this effect is intrinsically correlated with the overexpression of HDAC2 in cancer, leading to an aberrant alteration of immune response or, conversely, is also present in normal cells in specific settings, remains to be determined." (PMID 25473896, 2015). "One possible scenario is that cancer cells might ‘learn’ from normal cells, mimicking a normal and likely transitory repressive regulation possibly exerted by HDAC2 on its MHC targets during the life span of normal cells." (PMID 25473896, 2015). "It is tempting to speculate that HDAC2 (and possibly other HDACs) may act as a connecting bridge between immune response modulation and cancer development." (PMID 25473896, 2015). "The presence of high expression levels of other HDACs may influence the response of cancer cells to HDACi even when HDAC2 is silenced." (PMID 25473896, 2015). "Importantly, HDAC1 and HDAC2 are dysregulated in many human diseases including diabetes, asthma, neurological disorders and cancer." (PMID 25970771, 2015). "CBX7 contributes, in fact, to prevent cancer progression by positively regulating the expression of the E-cadherin through the interaction with the HDAC2 protein and the following inhibition of the HDAC2 activity." (PMID 25595895, 2015). "Proteins that control histone deacetylation, such as HDAC1 and HDAC2, are elevated in cancer cells." (PMID 24489651, 2014). "Also, the role of HDAC2 in protecting cancer cells against apoptosis has been demonstrated in gene knockout studies." (PMID 24275784, 2012). "Surprisingly, down-regulation of HDAC2 resulted in significantly decreased apoptosis induced by cytarabine, even though it was previously reported that down-regulation of HDAC2 is critical for inducing apoptosis in cancer cells." (PMID 21359182, 2011). "With these in vitro anti-tumor effects of HDAC2 inhibition, we demonstrated a remarkable suppression of tumor mass growth in vivo and a lower tumor incidence by using these cell lines in an experimental mouse xenograft model for cancer." (PMID 22132221, 2011).
cancer (continued). "Notably, computational approaches such as BENEIN have demonstrated the potential of perturbing HDAC2 as master regulator to drive differentiation and revert cancer cells to normal-like states, reinforcing the significance of our findings on VPA’s role as an HDAC inhibitor." (PMID 40750758, 2025). "Therefore, we suggest that HDAC2-high expressing cancer patients who exhibit stem cell-like tumor phenotype might benefit from the combination therapy, including both class I HDAC and immune checkpoint inhibitors." (PMID 39063083, 2024). "Similarly, the development of a first-in-class anti-cancer dual HDAC2/FAK inhibitor featuring hydroxamates/benzamides capped by pyridinyl-1, 2, 4-triazoles further emphasizes the importance of simultaneous targeting of multiple pathways critical for tumor growth." (PMID 38683491, 2024). "Thus, an miR-145 mimic could be developed as an anti-cancer drug targeting HDAC2-expressing cancers." (PMID 36968022, 2023). "This implies that HDAC2 could contribute to the stem cell-like properties of cancer cells." (PMID 36968022, 2023). "Thus, HDAC2 could promote cancer cell proliferation and tumorigenesis by regulating the cell cycle, tumor suppressor genes, EMT, and cancer stem cell-like properties." (PMID 36968022, 2023). "Many reports have indicated that HDAC2 could serve as a target for developing anti-cancer drugs." (PMID 36968022, 2023). "It is also probable that HDAC2 could be a prognostic cancer marker." (PMID 36968022, 2023). "In addition, the Rbx1, Hdac2, and Pik3r2 are involved in the signaling pathway of cancer cells." (PMID 35468821, 2022). "Here, we explore some of the top ranked TRs including histone deacetylase 2 (HDAC2), estrogen receptor 1 (ESR1), TEA domain family member 4 (TEAD4), achaete-scute homolog 1 (ASCL1), androgen receptor (AR) and yes associated protein 1 (YAP1) in several cancer types." (PMID 33778495, 2021). "It is probable that HDAC1 and HDAC-2 might be able to confer resistance to anti-cancer drugs." (PMID 30583572, 2018). "However, the mechanism by which USP4 mediates HDAC2 de-ubiquitination contributing to cancer remains unclear." (PMID 30071870, 2018). "Our study provides new insights into functions of HDAC2 in human cells that are both conserved within the Class I HDAC family and unique to HDAC2, which may aid future studies in distinguishing the precise roles of HDAC2 in contributing to certain types of cancer and in normal development." (PMID 28982113, 2017). "The presence of HDAC2 frame shift mutation in cancers from individuals with hereditary non-polyposis colorectal cancer syndrome caused a loss of HDAC2 protein expression and enzymatic activity and rendered tumour cells more resistant to trichostatin A, a pan-HDACi." (PMID 27283986, 2016). "This revealed that cancer‐derived iPSCs exhibited high levels of MYC and the histone deacetylase 2 (HDAC2), but decreased levels of TFEB, compared to the parental fibroblasts." (PMID 41097905, 2025). "Compound 7p, in particular, displayed strong affinity for key cancer-related targets such as HSP90, IGF1R, HDAC2, CDK6, HDAC8, and PIK3CA, all of which are involved in tumour proliferation, survival, and metastasis." (PMID 41463373, 2025). "The most commonly overexpressed genes in rare cancers included BIRC5 (88%), TOP2A (85%), CDK4 (82%), BRIP1 (76%), MSH6 (66%), and HDAC2 (62%)." (PMID 38347552, 2024). "In our study, aberrant HDAC2 overexpression led to the transcriptional silencing of NLRP3 and suppressed cancer cell pyroptosis." (PMID 38804602, 2024). "Histone deacetylase 2 (HDCA2), a protein abnormally expressed in different types of cancer, forms a target for novel selective inhibitors through epigenetic modulation." (PMID 38730621, 2024). "Given the dual function of TET2 in cancers, these findings demonstrate that a transcriptional complex of DNMT3a, TET2 and HDAC2 exists in sorafenibR HCC cells." (PMID 38528605, 2024).
cancer (continued). "Thus, HDAC2 might play a key role in anti-cancer drug resistance." (PMID 36968022, 2023). "For example, Entinostat (MS-275), which is currently in clinical trials for cancer treatment, selectively inhibits HDAC1, HDAC2, and HDAC3 with an IC50 of 0.54, 0.61, and 0.62 μM, respectively." (PMID 37759724, 2023). "Demonstrating antioxidant and anti-inflammatory effects, SFN activates NRF2 under oxidative stress conditions, and suppresses cancer cell growth, including HCT116 human colorectal carcinoma cells, by inhibiting HDAC2 and HDAC3 activities." (PMID 37298289, 2023). "Thus, HDAC2 might mediate EGFR signaling to promote cancer cell proliferation." (PMID 36968022, 2023). "Thus, HDAC2-specific inhibitor could be developed as anti-cancer drugs." (PMID 36968022, 2023). "HDAC3, HDAC10, HDAC2, HDAC7, ATAD2B were significantly upregulated in 9, 14, 13, 9, and 10 cancer types, respectively, whereas KAT2B was downregulated in 16 cancer types." (PMID 37553641, 2023). "Additionally, the latest evidence has shown that histone deacetylase 2 inhibition can regulate PD-L1 acetylation, thereby blocking the nuclear translocation of PD-L1 and consequently enhancing the efficacy of PD-1/PD-L1 inhibitors and improving anti-cancer immunity." (PMID 37716965, 2023). "Our results identified TRPS1 as a novel cofactor of PR-dependent recruitment by specifically binding to HDAC2, a member of corepressor complex, changing acetylation levels of the target gene RANKL, inducing its different expressions in different cancer cells." (PMID 37344459, 2023). "Regulated by a histone deacetylase 2-mediated epigenetic mechanism, the METTL14-miR-99a-5p-tribble 2 positive feedback loop promotes radiotherapy resistance and cancer stem cell persistence in ESCC." (PMID 37744275, 2023). "In total, 31 genes were overlapped in both datasets and 12 genes (i.e., CNBP, HDAC2, LDAH, RPL6 and EIF4G2) were annotated in Cancer Gene Census or CancerMine38,39." (PMID 36681772, 2023). "But in cancer, monocyte preferentially differentiates to PMN-MDSC through epigenetic silencing of the retinoblastoma (Rb) protein gene mediated by histone deacetylase 2 (HDAC-2)." (PMID 36439186, 2022). "The RT-qPCR method revealed that EGCG triggered anti- cancer epigenetic alterations, including downregulation of epigenetic regulators DNMT1, HDAC1, HDAC2, and G9a." (PMID 35327559, 2022). "TWIST1 also co-purified with NuRD complex, including MTA2, HDAC2, and RbAp48 in SW480 cells, which is consistent with previous findings in other cancer cell lines." (PMID 35884488, 2022). "Class I histone deacetylases, HDAC1, HDAC2, and HDAC3, represent potential targets for cancer treatment." (PMID 35458724, 2022). "To test the direct regulatory link, we knocked down HDAC2 and EZH2 expression using siRNAs in the cancer cell lines, and found that EZH2 and HDAC2 silencing in the cells significantly decreased PDK1 expression." (PMID 35892859, 2022). "For example, CBX7 positively regulated E-cadherin expression by inhibiting HDAC2 and PRMT1 activity on the E-cadherin promoter, and thereby suppressed cancer progression." (PMID 34035231, 2021). "Conversely, knockdown of ADGRG6 results in low expression of HDAC2 and GLI2, and inhibits proliferation and arrests cell cycle in cancer cells." (PMID 34809653, 2021). "HPV integration is most frequently detected in genic regions, most often cancer-related genes, such as oncogenes (e.g., TP63, MYC, ERBB2) or tumor suppressor genes (e.g., BCL2, FANCC, HDAC2, RAD51B, CSMD1) and to a lesser extent in miRNA regions." (PMID 34439243, 2021). "We explored here the expression profile of HDAC family via Oncomine database, which indicated that HDAC1, HDAC2, HDAC3, HDAC7, HDAC8, and HDAC9 expressed highly in pan‐cancer at transcriptional level." (PMID 34308568, 2021).